MIR584 (microRNA 584)
Synonyms: hsa-mir-584; MIRN584
Gene: MicroRNA gene on chromosome 5 (149,062,313 to 149,062,409, reverse strand). Ensembl gene ENSG00000207714.
Gene Ontology:
Biological process: miRNA-mediated post-transcriptional gene silencing
Cellular component: RISC complex
Homologues: Orthologues: chimpanzee ptr-mir-584 (100% identical), macaque mml-mir-584 (99% identical).